DPP6 (dipeptidyl peptidase like 6)
Description:
Promotes cell surface expression of the potassium channel KCND2. Modulates the activity and gating characteristics of the potassium channel KCND2. Has no dipeptidyl aminopeptidase activity.
Synonyms: DPPX; DPL1; MRD33; VF2
Tractability: Small molecule: it has a high-quality binding pocket; it belongs to a druggable protein family. Antibody: UniProt places it where antibodies can reach, with high confidence; UniProt predicts a signal peptide or a membrane-spanning region; its Gene Ontology location is reachable by antibodies, with medium confidence. PROTAC: its protein half-life has been measured.
Safety:
Unwanted effects reported when the protein is acted on. In parentheses: how it was acted on, where the effect was seen, and who reports it.
alcoholism (source: ClinPGx)
tardive dyskinesia (source: ClinPGx)
Gene: Protein-coding gene on chromosome 7 (153,748,133 to 154,894,285, forward strand). Ensembl gene ENSG00000130226.
Subcellular location: Cell membrane
Gene Ontology:
Molecular function: dipeptidyl-peptidase activity; potassium channel regulator activity; protein binding; serine-type peptidase activity
Biological process: regulation of potassium ion transmembrane transport; protein localization to plasma membrane; proteolysis
Cellular component: membrane; plasma membrane; voltage-gated potassium channel complex
Genetic constraint (gnomAD): Loss-of-function variants: 56 observed, 93.21 expected, observed/expected ratio (o/e) 0.6, 90% interval 0.48 to 0.75. The upper end of that interval is the gene's LOEUF score, 0.75, which puts it in group 3 of 6, group 1 being the genes least tolerant of losing a copy. Missense variants: 837 observed, 952.98 expected, observed/expected ratio (o/e) 0.88, 90% interval 0.83 to 0.93. Synonymous variants: 370 observed, 359.16 expected, observed/expected ratio (o/e) 1.03, 90% interval 0.94 to 1.12.
Gene-disease validity (ClinGen):
ClinGen rates the evidence that DPP6 causes each of these diseases.
complex neurodevelopmental disorder (autosomal dominant): Disputed. A disorder that involves more than one phenotype associated with the central nervous system, including but not limited to intellectual disability, autism, and seizures (epilepsy).
Homologues: Orthologues: macaque DPP6 (98% identical), dog DPP6 (94% identical), rat Dpp6 (93% identical), guinea pig DPP6 (92% identical), mouse Dpp6 (92% identical), pig DPP6 (92% identical), chimpanzee DPP6 (91% identical), rabbit DPP6 (81% identical), tropical clawed frog dpp6 (70% identical), zebrafish dpp6b (59% identical), zebrafish dpp6a (58% identical), Drosophila melanogaster CG3744 (17% identical), and 1 more. Paralogues in human: DPP10 (48% identical), FAP (28% identical), DPP4 (28% identical), DPP9 (21% identical), DPP8 (20% identical), APEH (14% identical).
Diseases named in the same sentence as DPP6 in open-access papers:
DPP6 is named in the same sentence as 97 diseases in open-access papers, as found by Europe PMC text mining. Sharing a sentence is not in itself a finding about the gene and the disease. The quoted sentences say what the papers report.
amyotrophic lateral sclerosis (10 papers, 2010 to 2025). Amyotrophic lateral sclerosis (ALS) is a neurodegenerative disease characterized by progressive muscular paralysis reflecting degeneration of motor neurons in the primary motor cortex, corticospinal tracts, brainstem and spinal cord. "Many studies suggest that DPP6 is consistently and strongly associated with susceptibility to amyotrophic lateral sclerosis (ALS) in different human populations of European ancestry." (PMID 35368668, 2022). "DPP6 has been associated with pancreatic cancer, tardive dyskinesia and amyotrophic lateral sclerosis in prior studies." (PMID 26545240, 2015). "This can especially be seen in the supporting findings that DPP6 is associated with neurodegenerative diseases and cognitive disorders such as amyotrophic lateral sclerosis, dementia, intellectual disability, Tourette’s syndrome, microcephaly, and autism spectrum disorder in addition to others." (PMID 36012450, 2022). "An acceleration of apoptosis is a proposed factor in the causes of amyotrophic lateral sclerosis (ALS), a neurodegenerative disease associated with DPP6 and caused by degeneration of motor neurons." (PMID 22675523, 2012). "Abnormal DPP6 expression has been identified in several diseases, such as amyotrophic lateral sclerosis (ALS), autism spectrum disorder (ASD), spinal bulbar muscular atrophy (SBMA), and idiopathic ventricular fibrillation." (PMID 40109277, 2025). "Both DPP6 and FGGY genes have been associated with an increased susceptibility for sporadic amyotrophic lateral sclerosis." (PMID 39857271, 2025). "This may, at least in part, explain DPP6′s association with neurodegenerative diseases and cognitive disorders such as amyotrophic lateral sclerosis (ALS), dementia, Tourette’s syndrome, microcephaly, and autism spectrum disorder (ASD) in addition to other illnesses or disabilities." (PMID 36012450, 2022). "Differential methylation was reported in RAD9B and C8orf46, CCNF, DPP6, RAMP3, and CCS genes in monozygotic twins and triplets discordant for amyotrophic lateral sclerosis." (PMID 34200232, 2021). "This gene, DPP6, has been proven as a candidate gene for amyotrophic lateral sclerosis (ALS) in the patients with ALS against the non-ALS population and could also be a potential factor that led to mental diseases, such as autism and posttraumatic stress disorder (PTSD)." (PMID 34639784, 2021).
autism (8 papers, 2011 to 2023). Persistent deficits in social interaction and communication and interaction as well as a markedly restricted repertoire of activity and interest as well as repetitive patterns of behavior. "The 125 kb microduplication at 7q36.2 disrupted the DPP6, whose mutations were associated with autism, autosomal dominant microcephaly, intellectual disability, and neurodegenerative dementia." (PMID 34659328, 2021). "The top-ranked clique in our analysis (hereafter will be referred as Clique I), was delineated by the autism genes: Ptchd1, Galnt13, Dpp6 and Astn2, and included another 29 genes, inter-connected with a co-expression values of ≥70%." (PMID 23935468, 2013). "By examining our expanded list of genes, we found several more of our connectivity linked genes are in AUTS1 and have been studied in the context of autism: Reln, Mest, Ptprz1, Dpp6 and En2." (PMID 21253556, 2011). "Dipeptidyl peptidase VI (DPP6) is located on chromosome 7q36, and its differential expression of the DPP6 gene has been linked to spinal cord injury in rats and is a potential candidate for autism." (PMID 37108335, 2023). "An individual who had a sensory processing disorder, apraxia, and autism, and was from a family with a variable psychiatric disorder, had mutation and disruptions in both DPP6 and LRRC4C genes, even though the variant by itself was not cause the autism." (PMID 36012450, 2022). "Exonic CNVs of NLGN1 and DPP6 have been identified in individuals with autism." (PMID 27777633, 2016). "Both rs7780487 and rs12536378 are on the autism candidate gene DPP6 on chromosome 7." (PMID 23281790, 2012).
dementia (7 papers, 2019 to 2026). Loss of intellectual abilities interfering with an individual's social and occupational functions. "Overall, they found that the loss of DPP6 expression and function can have a significant impact in dementia." (PMID 36012450, 2022). "An important recent study showed DPP6 to be a novel gene in dementia, finding enhanced rare variants and nonsense, frameshift and missense mutations in early Alzheimer’s disease (AD) and frontotemporal dementia patient cohorts." (PMID 33225987, 2020). "Taken together our data and these studies point toward a deleterious effect of DPP6 loss and support its contribution to dementia." (PMID 30874922, 2019). "The genetic association with rare variants is an additional line of genetic evidence to link DPP6 to dementia." (PMID 30874922, 2019). "Taken together, the results of our genomic, genetic, expression and modeling analyses, provided direct evidence supporting the involvement of DPP6 loss in dementia." (PMID 30874922, 2019). "Since dementia is a hallmark symptom of Alzheimer’s disease (AD), DPP6, as a protein closely associated with learning and memory, could be considered one of many candidate proteins involved in the pathogenesis of AD." (PMID 40109277, 2025). "DPP6 plays a crucial role in neuronal excitability and is also associated with dementia." (PMID 33805312, 2021). "Our findings demonstrate that DPP6, in addition to its effects on early synapse development appears to be important for the maintenance of synaptic function during aging as its loss leads to an increase in abnormal synaptic structures associated with physical and biochemical markers for dementia." (PMID 33225987, 2020). "Overall, these findings provided basic information for understanding possible roles of DPP6 in aging and the pathophysiology of diseases such as AD/dementia." (PMID 33225987, 2020). "Our findings of DPP6, as novel gene in dementia, strengthen the involvement of neuronal hyperexcitability and alteration in the homeostasis of neuronal firing as a disease mechanism to further investigate." (PMID 30874922, 2019). "These extracellular vesicles can transport their contents across the blood–brain barrier, suggesting that the DPP6 content in serum extracellular vesicles could serve as a potential biomarker for dementia." (PMID 40109277, 2025). "Our findings on DPP6, as a novel genetic factor in dementia, provide supportive evidence to the emerging concept that neuronal hyperexcitability and alteration of the homeostasis of neuronal firing represent a relevant disease mechanism warranting further investigation." (PMID 30874922, 2019).
Alzheimer disease (6 papers, 2019 to 2025). A progressive, neurodegenerative disease characterized by loss of function and death of nerve cells in several areas of the brain leading to loss of cognitive function such as memory and language. "Together these results indicate that aging DPP6-KO mice have increased numbers of novel, abnormal presynaptic structures associated with several markers of Alzheimer’s disease." (PMID 33225987, 2020). "Given the strong association of DPP6 with Alzheimer’s disease and frontotemporal dementia, as well as the shared features among ALS, MS, and SBMA, it is worth considering whether these complex neurodegenerative diseases share a common molecular mechanism potentially linked to DPP6 dysfunction." (PMID 40109277, 2025). "Immunofluorescence imaging showed that a number of markers for aging and Alzheimer’s disease were found at higher levels in the novel structures of aging DPP6-KO mice compared to WT." (PMID 36012450, 2022). "All these results indicate that aging DPP6-KO mice show characteristic symptoms similar to those found in Alzheimer’s disease, i.e., progressive cognitive and learning and memory impairment resulting from synapse loss and neuronal death." (PMID 36012450, 2022). "They found a specific late reduction in DPP6 in the olfactory bulb of patients with Alzheimer’s disease." (PMID 36012450, 2022). "Immunofluorescence imaging then showed that a number of markers for aging and especially Alzheimer’s disease were found as higher levels in these novel structures in aging DPP6-KO mice compared to WT." (PMID 33225987, 2020). "Recent research has indicated a connection between DPP6 and Alzheimer’s disease as well." (PMID 40109277, 2025). "In addition to exhibiting impaired hippocampal-dependent learning and memory abilities and reduced brain size, DPP6-KO mice display early-onset deposition of Alzheimer’s disease-related proteins, including amyloid β, α-synuclein, and phosphorylated tau." (PMID 40109277, 2025). "DPP6 resequencing identified significantly more rare variants—nonsense, frameshift, and missense—in early-onset Alzheimer’s disease (EOAD, p value = 0.03, OR = 2.21 95% CI 1.05–4.82) and frontotemporal dementia (FTD, p = 0.006, OR = 2.59, 95% CI 1.28–5.49) patient cohorts." (PMID 30874922, 2019).
breast carcinoma (6 papers, 2013 to 2024). "High expression levels of DPP3 and DPP4 were associated with poor survival of breast cancer patients, whereas high expression levels of DPP6, DPP7, DPP8, and DPP9 were associated with good prognoses." (PMID 34359286, 2021). "Additionally, high expression of DPP6 was reported to be correlated with good prognoses in patients with breast cancer." (PMID 35565241, 2022). "To further validate the identified target genes that showed significant changes in DE and DM patterns in response to maternal BSp treatment, we evaluated gene expression of Avpr2, Cyp4a12b, Dpp6, Gria2, Pcdh9 and Tspan11 genes in the offspring mammary tumors using qRT-PCR." (PMID 35263365, 2022). "In parallel studies for downregulated genes, we were able to identify seven genes with mutations in colon cancer (DPP10, PCSK2, ADAM33, RELN, CAPN13, ADAMTS1 and ADAMTS15), and five genes with mutations in breast carcinomas (MASP3, ABHD12B, TLL1, CPA3 and DPP6)." (PMID 24243807, 2013). "In breast cancer tissues, DPP6 has low expression at the transcription and protein levels, and in breast cancer patients, low expression of DPP6 indicates poor prognoses, suggesting that DPP6 may serve as a tumour suppressor in tumour development, which agreed with our study." (PMID 36531033, 2022). "Our data showed that DPP6 had low expression levels in breast cancer tissues at both the transcription and protein levels, and was further related to good prognoses in breast cancer patients, which also suggested that DPP6 may act as a tumor suppressor in cancer development." (PMID 34359286, 2021). "Results from an Oncomine analysis showed that mRNA expression levels of DPP3 and DPP9 were highly upregulated in breast cancer tissues, whereas DPP4, DPP6, and DPP8 exhibited downregulated levels in breast cancer tissues relative to normal breast tissues." (PMID 34359286, 2021). "This family comprises seven members, including DPP3, DPP4, DPP6, DPP7, DPP8, DPP9, and DPP10; however, information on the involvement of DPPs in breast cancer is lacking in the literature." (PMID 34359286, 2021).
colon cancer (6 papers, 2012 to 2022). "It was reported that DPP6 was down-regulated in acute myeloid leukemia and melanoma but up-regulated in colon cancer, which was probably caused by hyper- and hypomethylation, respectively." (PMID 32002016, 2020). "Our present findings indicate that high DPP6 expression worsens survival of ESCA patients which is in line with previous data regarding colon cancer progression." (PMID 35361846, 2022). "The DPP6 gene was reported as a hypomethylated gene in colon cancer and at the same time is considered as a biomarker for melanoma." (PMID 22479372, 2012). "Similarly, hypomethylation and subsequent increased expression of Dpp6 is observed during colon cancer progression." (PMID 23409053, 2013). "Hypomethylation and increased expression of Dpp6 gene is found in colon cancer." (PMID 23409053, 2013).
Arrhythmia (5 papers, 2018 to 2026). Any cardiac rhythm other than the normal sinus rhythm. "Furthermore, prolonged QT/QU intervals on an electrocardiogram (ECG) indicate delayed cardiac repolarization and an increased risk of arrhythmias; DPP6 mutations may contribute to these abnormalities, thereby increasing arrhythmia susceptibility." (PMID 40109277, 2025). "Most of these variants were located in genes associated with inherited arrhythmias and arrhythmic cardiomyopathies, such as MYBPC3, KCNQ1, TTN, CASQ2, GPD1L, DPP6, HCN4 and NEXN." (PMID 36008935, 2022). "We also identified five potentially pathologic variants in genes associated with cardiac arrhythmia, including KCNMB1, KCNIP1, DPP6, JUP, F2, and TUBA3D that were identified in SUDEP patients but not present in our living epilepsy cases." (PMID 29619247, 2018). "The inherited arrhythmia syndromes most strongly associated with mental stress-induced arrhythmias and SCA are long QT syndrome type 2 (LQTS2), catecholaminergic ventricular tachycardia (CPVT) and an idiopathic VF syndrome linked to a risk haplotype that contains the DPP6 gene." (PMID 35185641, 2021).
idiopathic ventricular fibrillation (5 papers, 2018 to 2025). "We identified DPP6, a gene implicated in familial form idiopathic ventricular fibrillation in the Dutch population and was associated with QT interval albeit at a suggestive level (p = 1.66 × 10−6) in the GWAS of African Americans." (PMID 40822352, 2025). "Proband s14 carried the splicing variant c.2078+5G>A in DPP6, which is a gene that is reported to be associated with idiopathic ventricular fibrillation." (PMID 36008935, 2022). "At the DPP6 locus from GWAS of factor 3 an additional signal rs113687675 was identified, and it is located at approximately 2,175 base pairs upstream of rs606231226, the variant reported for familial paroxysmal ventricular fibrillation in a Dutch family." (PMID 40822352, 2025). "Furthermore, a DPP6 mutation was detected in idiopathic ventricular fibrillation patients, which disturbs the efflux of potassium ion." (PMID 35783865, 2022). "Haplotype analysis in both familial and sporadic cases indicated the relevance of DPP6 with idiopathic ventricular fibrillation." (PMID 35783865, 2022).
Intellectual disability (5 papers, 2019 to 2025). "The most common symptoms resulting from DPP6 dysregulation are mental deficiency and muscle wastage." (PMID 40109277, 2025). "Loss of function of DPP6 is associated with autosomal dominant microcephaly, which can lead to varying degrees of intellectual disability." (PMID 40109277, 2025). "For instance, similar to WDFY3, mutations in DPP6, which encodes a dipeptidyl peptidase protein, cause autosomal dominant microcephaly in addition to intellectual disabilities, indicating that it may also be necessary to screen through heterozygous variants in patients." (PMID 33178111, 2020). "When researching patients with autosomal dominant microcephaly and intellectual disability (ID), it was found that DPP6 expression was reduced due to presence of a missense variation or deletion at the 7q36.2 loci in multiple subjects." (PMID 36012450, 2022). "Heterozygous loss of DPP6 may not represent a single cause of severe intellectual disability but it is likely a susceptibility factor to this phenotype." (PMID 30874922, 2019).
melanoma (5 papers, 2012 to 2022). A malignant, usually aggressive tumor composed of atypical, neoplastic melanocytes. "Hypermethylation and decreased expression of DPP6 were observed in endometrial cancer and melanoma while the role of DPP6 in LUAD is still unclear." (PMID 32688456, 2020). "This gene list also included genes that have roles in a variety of other cancers e.g. DPP6 is down regulated in melanoma, SPHKAP plays a role in the sphingosine phosphorylation pathway that induces tumor progression and invasion." (PMID 22479372, 2012).
autism spectrum disorder (4 papers, 2019 to 2025). A spectrum of developmental disorders that includes autism, and Asperger syndrome. "In addition, a significant enrichment among the nominal DEGs for genes implicated in autism spectrum disorder (ASD) was found (e.g., AFF2, DNER, DPP6, DPP10, RELN, CACNA1C), as well as several that are strong candidate genes for the development of eye problems found in LS, including glaucoma." (PMID 32393163, 2020).
Autosomal dominant microcephaly (4 papers, 2019 to 2021). "DPP6 is associated with autosomal dominant intellectual disability 33 (OMIM 616311)." (PMID 33584815, 2020).
frontotemporal dementia (4 papers, 2019 to 2025). Frontotemporal dementia (FTD) comprises a group of neurodegenerative disorders, characterized by progressive changes in behavior, executive dysfunction and language impairment, as a result of degeneration of the medial prefrontal and frontoinsular cortices. "Genetic variations in DPP6, including nonsense and frameshift variants as well as intronic SNPs, are associated with frontotemporal dementia (FTD)." (PMID 40109277, 2025).